IL6 (interleukin 6)
Diseases named in the same sentence as IL6 in open-access papers (continued):
Sharing a sentence is not in itself a finding about the gene and the disease.
tumor (continued). "Tobacco smoke exposure following K-ras driven tumor initiation in mice had a tumor-promoting effect, via the induction of low-grade inflammation characterized by NF-κB-mediated production of IL-6 and TNF-α." (PMID 35221216, 2021). "The M2d subtype, also known as tumor‐associated macrophages (TAMs), secretes TNFα, IL‐6, IL‐10, TGFβ, and VEGFA to promote tumor progression." (PMID 34136188, 2021). "Although the samples and data are limited, the trend is an inverse correlation of IL-6 RNA expression with these pro-apoptotic tumor suppressor genes, in support of our interpretations with IL-6 in Eμ-myc mice." (PMID 33651821, 2021). "IL-6 is a key proinflammatory cytokine within the gut, and it exerts a marked effect on the tumor microenvironment in a wide range of cancers." (PMID 34394377, 2021). "The expression of IL-6 has been demonstrated to correlate with the tumor development in several tumor types." (PMID 34657635, 2021). "This demonstrates that IL-6 is an important TME-derived paracrine factor that suppresses the generation of robust anti-tumor immunity." (PMID 34711820, 2021). "At the tumor site, both microglia and astrocytes contribute to a positive loop based on IL-6 production by microglia triggering astrocytes to release MCP-3, a chemokine attracting more microglial cells." (PMID 34949203, 2021). "In the current study, we found that IL-6 blockade enhanced Ang1 production by tumor cells, whereas siRNA-induced Ang1 depletion restored the impaired anti-angiogenic function of Bev under IL-6 blockade." (PMID 33833265, 2021). "NF‐κB is mainly activated in these cells to induce the expression of cytokines (TNFα, IL‐1β, IL‐6, etc.), thereby promoting tumor survival and proliferation." (PMID 34977871, 2021). "By analyzing the TCGA and GEO database and applying ESTIMATE algorithm and a series of bioinformatic methods, we obtained tumor microenvironment associated genes (CD79A, CXCL13, IL6 and CCL19), which were related to the clinical outcome of PRCC patients." (PMID 33993869, 2021). "Then, extracellular HMGB1 promotes the release of cytokines such as IL-6 and Tnf-α by activating MAPKs and Stat3 pathways, which stimulates tumor cells proliferation, angiogenesis, EMT, invasion, and metastasis." (PMID 35046917, 2021). "It is known that downstream of IL-1β, IL-6 and IL-8 promote tumor growth and invasion; specifically, IL-6 seems to be a poor prognostic factor for patients’ survival." (PMID 34209535, 2021). "Targeting of IL-6 directly or indirectly has therefore emerged as a strategy to limit the attraction of MDSCs or block their tumor-promoting functions." (PMID 35003065, 2021). "To investigate the effect of IL-6 blocking on tumor growth in vivo, we administered tocilizumab (IL-6R antibody) and apigenin, individually or together with paclitaxel, to mice bearing PDX tumors." (PMID 34588424, 2021). "In fact, IL-6 signals inhibit several immunocompetent cells activation in the tumor microenvironment." (PMID 33531609, 2021). "IL-6 expression is reported to be increase in a variety of tumors and to contribute to aggressive tumor growth and resistance to treatment." (PMID 34109109, 2021). "IL6 is secreted by the tumour-immune system axis and has pro-inflammatory effects, but also is a myokine that is quickly released by skeletal muscle itself in response to contraction and attenuates inflammation." (PMID 34359731, 2021). "This supports the notion that, even if lower levels of IL6 are produced endogenously in ER+ tumours, the cytokine still contributes to the advancement of ER-driven disease." (PMID 34834425, 2021).
tumor (continued). "The persistent activation of STAT3 mediates tumor-promoting inflammatory pathways, including nuclear factor-κB (NF-κB) and interleukin-6 (IL-6)–GP130–Janus kinase (JAK) pathways." (PMID 33509150, 2021). "Blocking IL-6 signaling obviously inhibits primary tumor growth and recurrence in orthotopic xenograft models." (PMID 34336821, 2021). "Tissue damage occurring during tumor development and the release of alarm cytokines such as IL-1α, IL-1β, and TNFα induce the production of IL-6, IL-10, IL-11, and IL-23 by tissues and myeloid cells." (PMID 33498483, 2021). "IL-6 also aids recruitment of circulating tumour cells back into their primary tumour site and accelerate tumor growth and angiogenesis." (PMID 34223877, 2021). "This elevated immune signature in tumor stroma seems to include increased expression of genes that are pathway components or recognized targets of IL-6 signaling, implying a potential compensatory response to decreased IL-6 pathway flux." (PMID 34711820, 2021). "Combination BRAF-MEKi can shape the tumor microenvironment by reducing immunosuppressive factors such as vascular endothelial growth factor, IL-6, IL-10, and TGF-β which corresponds with increasing tumor infiltrating lymphocytes." (PMID 34944961, 2021). "IL-6 is a critical mediator stimulated by a variety of cells, including T lymphocytes, epithelial cells, monocytes, macrophages, and tumor cells." (PMID 34337082, 2021). "Neutrophils secrete factors that stimulate tumor progression, such as interleukin-2 (IL-2), interleukin-6 (IL-6), interleukin-10 (IL-10), tumor necrosis factor α (TNF-α), and vascular endothelium growth factor (VEGF)." (PMID 34830745, 2021). "Here, we found that even with increased IL-6 and FoxO3 expression in both tumour-bearing groups, leucine supplementation blunted the expression of key catabolic related proteins, MuRF-1, and 20S." (PMID 34943780, 2021). "The increased production of IL-6 and IL-8 by tumor cells can be explained through glycosylation of proteins, β-glucans, or chitins of the C. albicans cell wall by mannosyl residues or by the production of aspartate proteases (SAPs) by the yeasts." (PMID 34442627, 2021). "Within the tumor microenvironment, the OC cells and other stromal cells secrete proinflammatory cytokines, such as IL6 and others." (PMID 34945807, 2021). "IL-6/STAT3 signaling was reported to stimulate tumor invasion, EMT and promote the survival of tumor cells after therapy to acquire treatment resistance." (PMID 34109109, 2021). "A correlation of immune cell marker genes, including tumor-associated macrophages (TAMs) (CD209, CD206/MRC1, IL6, IL8, and CXCL10), MDSCs (CD33 and IL6), dendritic cells (DCs) (CD11c/ITGAX, CD209, TNF, and CD80) and Fusobacterium has been found in humans." (PMID 33823861, 2021). "Contrarily, recent studies have reported the anti-tumor effect of IL6, which plays a key role in the activation, proliferation, and survival of lymphocytes during active immune responses by mobilizing anti-tumor T-cell immune responses." (PMID 34790130, 2021). "Functional data also support a role for IL-6 in PDAC tumor development, progression, metastasis, antitumor immunity, and response to chemotherapy." (PMID 33851955, 2021). "IL-6 is an important cytokine in the tumour microenvironment, but its role in regulating autophagy in cancer cells is unclear." (PMID 34131122, 2021). "IL6 seems to act as an autocrine and paracrine signal triggering tumor cell migration and invasion, as well as EMT." (PMID 34205944, 2021). "Tumor cells subsequently increased oxidative phosphorylation and decreased glycolysis partially via IL-6." (PMID 34771503, 2021). "Accumulating evidence has emerged suggesting IL-6 as a vital factor for MDSC activity in the tumor microenvironment." (PMID 34689842, 2021).
tumor (continued). "IL-6 can promote the retrodifferentiation of tumor-derived HepaRG hepatocyte-like cells (HepaRG-tdHep) into proliferative stem/progenitor cells through the interaction between TNF–α and TGF-β." (PMID 35096588, 2021). "In turn, such CAF-like cells were demonstrated to promote proliferation and cisplatin resistance of tumor cells through the secretion of IL-6." (PMID 33572359, 2021). "In tumor microenvironments, IL-6 signaling not only promotes proliferation and survival but also has anti-tumor effects due to inhibition of tumor growth through T-cell immune response." (PMID 34267603, 2021). "Our results indicated that Agrin promotes tumor cell growth and Treg infiltration via increasing IL-6 expression and secretion through PI3K/AKT pathway in NSCLC." (PMID 35111682, 2021). "To explore the mechanism by which hypoxia elicits inflammation in lung tumors, we studied IL1A and IL6 expression in tumor cells and macrophages in response to hypoxic stress." (PMID 34362882, 2021). "We identify a Stat3/HIF-1α-mediated axis, through which IL-6 executes an anti-tumor role to induce CD40 expression in Mφs." (PMID 34103524, 2021). "The activation of innate immune receptors, such as Toll-like receptors (TLRs), via IL-6 induction through a universal TLRs adaptor, MyD88, plays a considerable role in tumor development in the liver." (PMID 33668122, 2021). "In response to this, tumor cells produce more IL-6 and IL-8 thereby fueling a feed-forward loop and enabling a continuous supply of nutrients from adjacent CAFs." (PMID 34858425, 2021). "In sum, our work uncovers a complex role for IL-6 in regulation of tumor immunity: IL-6 induces alternative Mφ polarization and anti-inflammatory immune suppression, whereas it stimulates pro-inflammatory CD40 expression via Stat3/HIF-1α in GBM." (PMID 34103524, 2021). "Eμ-myc expression reduced peripheral CD4 and CD8 T cells in pre-tumor spleens of both IL6+/+;Eμ-myc and IL6-/-;Eμ-myc mice." (PMID 33651821, 2021). "Uncontrolled expression of IL6 is responsible for several autoimmune inflammatory diseases and tumor growth." (PMID 35126382, 2021). "As a result, the production of cyclic adenosine monophosphate (cAMP), IL-6, and IL-12 are inhibited, which dampens immune response and accelerates tumor growth." (PMID 34988072, 2021). "Circulating tumor-derived PTHrP, MIP-1α, IL-1, IL-6, and TNF-α have been identified in the serum of ATL patients and are factors underlying the clinical tumor-associated bone manifestations." (PMID 34680215, 2021). "As a myokine, IL‐6 has been indicated to play an important role in the redistribution and infiltration of natural killer cells, thereby suppressing tumour growth." (PMID 32478975, 2021). "The pathological feature of NPC tumor microenvironment (TME) is that it releases a large amount of inflammatory messengers such as cytokines (TNF-α, IL-6), which causes immune cell infiltration and promotes tumorigenesis." (PMID 34165442, 2021). "Disseminated tumor cells secrete IL-6, which attracts TAMs contributing to tumor cell proliferation and angiogenesis in bone sites in an in vivo mouse model." (PMID 34595122, 2021). "IL-6 is a multifunctional cytokine, which plays an important role in regulating immune response, hematopoietic system, tumor metastasis and endocrine system." (PMID 34150667, 2021). "By contrast, IL6 immunohistochemistry performed in our sample set showed positive staining only in tumor cells, with some tumor areas presenting a strong cellular membrane and cytoplasmic, and intercellular staining (probably as a result of IL6 secretion)." (PMID 34422669, 2021). "Our study shows that it exists the crosstalk between cancer cells and macrophages in muscle tissues that tumor cells secrete IL-6 inducing macrophages to up-regulate MMP12." (PMID 34863141, 2021).
tumor (continued). "Inflammatory cells often act as a critical source of various tumor-promoting inflammatory mediators, including ROS, cytokines such as TNF, IL-1, and IL-6, and growth factors that directly or indirectly support the entire process of tumor development." (PMID 34063828, 2021). "It has been proposed that tumor necrosis factor-a and interleukin-6 (IL-6), secreted by tumor cells, can reduce hemoglobin levels by altering the hematopoietic environment." (PMID 33974528, 2021). "IL-6 powerfully stimulating the activation of the JAK/STAT3 pathway to promote tumor proliferation, motility, and invasion." (PMID 33953676, 2021). "The antibacterial and anti-tumor immune responses from the M1 macrophages are executed by releasing pro-inflammatory cytokines (such as IL-12, IL-1β, IL-2, IL-6, IL-23, and TNF-α), NO, ROS, and chemokines." (PMID 33883988, 2021). "IL6 and TNFα promote tumor angiogenesis through increasing vascular endothelial growth factor (VEGF) expression." (PMID 33579265, 2021). "IL-6 is known to promote tumour proliferation and resistance to chemotherapy and to trigger epithelial-to-mesenchymal transition, leading to cancer metastasis." (PMID 34928453, 2021). "In turn, blocking IL-6 resulted in a reduction of BC tumour growth and invasive ability due to a decrease in cell proliferation, lower epithelial–mesenchymal transition, reduced DNA methyltransferase 1 expression and attenuated angiogenesis." (PMID 33923108, 2021). "Anti-tumor effects of IL-6 include lymphocyte trafficking to lymph nodes, proliferation, activation, and polarization to phenotypes that have anti-tumor effects." (PMID 34214127, 2021). "Neutrophils are important components of several inflammatory responses, including interleukin-6 (IL-6), which has dual tumor development and metastasis roles." (PMID 34774016, 2021). "We demonstrate that the cross talk between the tumor and distant BM niche is mediated by IL-6/IL-6Ra signaling, paving the way toward new therapeutic approaches to target metastasis." (PMID 34140316, 2021). "To address these concerns, we measured the cytokines (such as TNF-α, IL-1β and IL-6) after we intravenously administered DMVs at 0.6 mg of DMVs which was the same dose used in the tumor therapy." (PMID 33537088, 2021). "IL-6 crosstalk between tumour cells and GCAFs not only supports tumour growth, but also promotes CAFs activation through IL-6Rα." (PMID 33810350, 2021). "IL-17 can promote tumor formation by triggering IL-6 secretion and subsequently activating the STAT3 pathway." (PMID 33578830, 2021). "Such signals which mediate their function by contact between tumour cells and fibroblast or by soluble factors such as IL-1 or IL-6, induce the CAF phenotype characterized by the expression of α-smooth muscle actin (α-SMA)." (PMID 34003341, 2021). "IL-6 appeared to be secreted by tumor cells and by fibroblasts and consumed by ECs; although further studies will be required to conclude on the role of IL-6, its concentration was not correlated with EC maintenance." (PMID 34178955, 2021). "For instance, the cytokines IL-6 and IL-10 activate the transcription factor STAT3, which inhibits in macrophages the genes encoding for anti-tumor cytokines." (PMID 34583655, 2021). "We detected by IHC the markers for autophagy (LC3 and p62) and for activated stromal fibroblasts (CAFs; with α-SMA) and for IL-6 in tumor specimens at Month 1 and 6 after cholangiocarcinogenesis, i.e., at early and late stages of stromal fibrosis." (PMID 33925189, 2021). "The accumulation of MDSC in tumor-bearing individuals has been shown to depend on the inflammatory mediators IL-1β, IL-6, and Prostaglandin-E2 (PGE2)." (PMID 33917501, 2021). "Other studies reported the normalization of laboratory values, including IL-6 levels, after resection of the tumour." (PMID 33715142, 2021). "In hepatocellular cancer, HCC progenitor cells acquired autocrine IL-6 signaling and thus promote the tumor proliferation." (PMID 34182543, 2021).
tumor (continued). "Tumor infiltration and activation of antigen-presenting cells and immune effector cells is mediated by several cytokines such as TNFα, IL-1β, IL-6 secreted in the tumor." (PMID 34830880, 2021). "In tumor-associated pathological conditions, various immune response-related molecules in TME such as IL-1β, IL-6, prostaglandin E2, VEGF, and IFN-γ induce abnormal accumulation of immature myeloid cells by impairing the differentiation process." (PMID 34576180, 2021). "A previous study reported that macrophages in the early stage of HCC express high levels of major histocompatibility complex (MHC)-class II and cytokines, such as IL-1β, IL-6, IL-12, and inducible nitric oxide synthase, which suppress tumor progression." (PMID 33854960, 2021). "Recently, IL-6–DNMT3b–mediated OCT4 expression was found to correlate with tumor early recurrence and poor prognosis of HCC patients." (PMID 33669204, 2021). "Based on these evidences, our results pave the way to identify new genetic and epigenetic biomarkers that are useful to predict the therapeutic response of tumor patients to biologic drugs direct towards IL6/STAT3 axis." (PMID 34576335, 2021). "A notable example is the inactivation of liver kinase B1 (LKB1), a tumor suppressor, which reportedly promotes neutrophil recruitment and pro-inflammatory cytokine (IL-1β, IL-6, IL-33, and CXCL7) production to suppress T cell infiltration and function." (PMID 34063828, 2021). "IL-6 was produced by a variety of cell types located in the tumor microenvironment, including tumor-infiltrating immune cells, stromal cells, and tumor cells themselves." (PMID 34712264, 2021). "There is robust evidence that elevated IL-6 expression correlates with tumor progression and consequently also with lower patient overall survival." (PMID 34681685, 2021). "The chemotherapeutic doxorubicin is curative in IL-6-deficient mice through the induction of CD8+ T-cell-mediated anti-cancer responses, while moderately extending lifespan in wild type tumor-bearing mice." (PMID 34711820, 2021). "IL-6, a major cytokine in the tumor microenvironment, is highly expressed in almost all types of tumors and promotes tumorigenesis by regulating all hallmarks of cancers and multiple signaling pathways." (PMID 33802402, 2021). "Such IL-6 can be the result of tumor cell IL-6 expression or production by a number of other cell types in response to DAMPs, hypoxia, or inflammatory mediators." (PMID 33922465, 2021). "Evidence is provided that the inflammatory cytokine IL-6 is a critical tumor promoter during early stages of Eμ-myc-driven B cell lymphomagenesis." (PMID 33651821, 2021). "Together with the findings here we can draw the conclusion that IL-6 inhibits tumor growth by promoting the expression of E/P-selectin and ICAM-1 via JAK/STAT3 pathway and consequently facilitating T cells infiltration." (PMID 33390844, 2021). "IL-6 and IL-8, derived either from tumors or their niche (which should also take up Bpep/Dpep), contribute to tumor growth, metastasis and therapeutic resistance." (PMID 34065488, 2021). "TNF-a, IL-6, and IL-8 are directly involved in tumor progression as well as indirectly through inductive VEGF expression." (PMID 34096454, 2021). "In PCs, IL-6 can be expressed by stromal and tumor cells, influencing the DC differentiation and function, which are inhibited by STAT3 activation." (PMID 34830209, 2021). "In the tumor microenvironment, IL-6/JAK/STAT3 signaling pathway plays a pivotal role in regulating the growth, survival, invasiveness, metastasis, and development of many cancers." (PMID 35155571, 2021). "With regard to cigarette smoking, significantly higher expression of IL-6 was observed in the tumour tissue of patients with a history of ≤ 40 PYs, i.e. 2.197 (IQR: 0.821–4.415) than in those with > 40 PYs, i.e. 0.461 (IQR: 0.372–0.741), (UMW test, p = 0.037)." (PMID 33658555, 2021).